INS (insulin)
Diseases named in the same sentence as INS in open-access papers (continued):
Sharing a sentence is not in itself a finding about the gene and the disease.
Insulin resistance (continued). "PPARγ agonists have been studied in the past; they were given as treatments both in vitro and in vivo, resulting in normalised serum insulin and glucose concentrations in insulin-resistance models." (PMID 24324517, 2013). "Metformin ameliorates insulin resistance by improving insulin sensitivity in liver and skeletal muscle." (PMID 23341947, 2013). "Affected dolphins have elevations in the serum iron and ferritin levels and exhibit elevation in serum insulin and glucagon concentrations 2-h after feeding, consistent with insulin resistance." (PMID 24348462, 2013). "In this study, the exposure of Fao rat hepatoma cells to 50 and 200 μg/mL of TiO2-NPs impaired insulin response and induced insulin resistance through direct interference with insulin-signalling pathways and indirect inflammatory activation of the macrophages." (PMID 23949635, 2013). "The triglycerides-increasing alleles of GCKR variants can reduce blood insulin and HOMA-IR index, and the risk of insulin resistance in Chinese children." (PMID 23383164, 2013). "Pancreatic beta-cells have the ability to increase insulin secretion (via AIRG) in response to insulin resistance." (PMID 23762538, 2013). "The resulting activation of caspase-1 and subsequent secretion of IL-1β then interfere with insulin signaling, whereas inhibition of caspase-1 has been demonstrated to attenuate insulin resistance coincident with improved function of adipocytes." (PMID 23964268, 2013). "Significant differences in fasting and 2-h glucose, fasting insulin, glycosylated haemoglobin (HbA1c), insulin resistance (HOMA-IR), and total cholesterol were observed across the dietary patterns." (PMID 23843779, 2013). "The association between the NLRP3 inflammasome and both insulin resistance and obesity has been suggested by animal studies showing that genetic ablation of NLRP3 improved insulin sensitivity and glucose homeostasis." (PMID 23843683, 2013). "We firstly observed that the GCKR variants of increasing triglycerides had lower the levels of insulin and HOMA-IR index, and reduce the risk of insulin resistance for Chinese children." (PMID 23383164, 2013). "Overall, the preexisting maternal diabetes leads to glucose intolerance, insulin resistance, and impaired insulin sensitivity and β-cell function in the offspring at different postnatal periods." (PMID 23998129, 2013). "Recent studies suggest that myostatin plays a major role in regulating insulin signaling and insulin resistance." (PMID 24454989, 2013). "Insulin resistance leads to a compensatory increase in insulin secretion, which enables sufficient control of blood glucose levels." (PMID 23781322, 2013). "While insulin, homeostasis model assessment-insulin resistance (HOMA-IR) and triglyceride (TG) values were detected to be significantly higher in the GDM cases especially after 32 weeks of gestation (p<0.001)." (PMID 24639763, 2013). "In subjects with cardiovascular disease, MPV was significantly elevated in those with insulin resistance when compared to insulin-sensitive subjects." (PMID 23311535, 2013). "Patients in the normal group had lower mean ALT, glucose, insulin, and homeostatic model assessment for insulin resistance (HOMA-IR) than those in the NAFLD group." (PMID 23658732, 2013). "Insulin resistance is accompanied by increased insulin levels that, in the presence of increased lipolysis and/or increased fat intake, promote hepatic triglyceride synthesis." (PMID 23666091, 2013). "The major finding of this study is that consumption of 4 servings/d of low-fat dairy milk and yogurt products under free-living conditions for 6 months reduced fasting plasma insulin (9%) and improved insulin resistance (11%) in overweight and obese adults." (PMID 23638799, 2013). "The HOMA-IR, a measure of insulin resistance, was calculated using fasting blood glucose and serum insulin levels from 10 week old mice." (PMID 24252636, 2013).
Insulin resistance (continued). "Our data proved that OXT and its analogs have the actions to reverse insulin resistance and improve insulin secretion in these mouse models." (PMID 23700406, 2013). "Subjects in any of the three states have moderate to severe insulin resistance and impaired insulin secretion, each state having distinct pathophysiologic etiologies." (PMID 24502249, 2013). "For GK rats, because of the reduced number of islets at birth, both insulin resistance and impaired insulin secretion are present at their adult lives, coupled with moderate but stable fasting hyperglycemia which is present at the end of the first 2 weeks." (PMID 23671868, 2013). "In contrast, insulin sensitizers such as TZDs (e.g., rosiglitazone and pioglitazone) and a biguanide, metformin, can directly lower insulin resistance and, subsequently, blood glucose." (PMID 23662132, 2013). "Future research aiming at the investigation of insulin resistance over and above the insulin-glucose axis therefore is necessary." (PMID 23866050, 2013). "Another prospective study on 31 morbidly obese patients followed up for a duration of 6 months showed that insulin sensitivity as estimated by the HOMA-IR was unchanged, but individual changes of insulin resistance and visfatin were significantly associated." (PMID 23690771, 2013). "The primary outcome, HOMA-IR, has been validated in assessing insulin resistance based on fasting plasma glucose and serum insulin levels in epidemiological studies." (PMID 23936766, 2013). "Fasting plasma glucose, body weight, food intake per 1 kg body weight, insulin and a homeostasis model assessment of insulin resistance (HOMA-IR) were measured pre- and post-surgery." (PMID 23737909, 2013). "FL83B mouse hepatocytes were treated with tumor necrosis factor-α (TNF-α) to induce insulin resistance to investigate the effect of a wax apple aqueous extract (WAE) in insulin-resistant mouse hepatocytes." (PMID 23389304, 2013). "Insulin resistance in PCOS is ascribed to defects in insulin signaling in adipocytes and skeletal muscle." (PMID 23349861, 2013). "Theoretically, insulin resistance is defined as a state in a cell, tissue, system, or body for which levels of insulin needed to produce a quantitatively normal response are greater than normal." (PMID 24324517, 2013). "It is important to note that insulin resistance occurs in an impaired insulin-signalling pathway, indicative of patients with type 2 diabetes." (PMID 24391675, 2013). "With systemic insulin resistance, insulin signaling within glucose recipient tissues is defective therefore hyperglycemia perseveres." (PMID 23542897, 2013). "By analogy, while for research purposes insulin resistance is determined by insulin clamp, for clinical purposes determination of fasting glucose and insulin are used." (PMID 23734252, 2013). "EATT was positively correlated with body mass index-SDS, waist circumference, fasting glucose, insulin, homeostasis model assessment-insulin resistance, triglyceride levels, LV thickness, LVMI, and MPI in the MS obese group." (PMID 24072083, 2013). "In most studies, serum glucose, insulin, and sometimes, fasting pro insulin and C-peptide have been measured and only indicators of insulin resistance and insulin sensitivity has been reported." (PMID 23870044, 2013). "It is well known that insulin resistance and hyperinsulinemia are closely associated with PCOS, and insulin-sensitizer drugs improve hirsutism in patients with PCOS, while there are not enough data showing that patients with HI also have insulin resistance." (PMID 24228029, 2013). "We elucidated a significantly increased insulin resistance with elevation in fasting plasma glucose +7.0(0.6) mg/dL, fasting insulin +5.7(1.4) uIU/ml and HOMA-IR +1.6(0.5)." (PMID 23347533, 2013). "Patient B, in contrast, demonstrated blood glucose and insulin levels during the eGTT more in agreement with insulin resistance." (PMID 23424590, 2013).
Insulin resistance (continued). "Biguanides improve insulin resistance and decrease the blood insulin concentration, and therefore the efficacy of these drugs for prevention of cancer has been evaluated." (PMID 23291663, 2013). "Insulin declines with the progression of fasting in humans, facilitating lipolysis while insulin resistance increases." (PMID 24198811, 2013). "Our data firstly find that the triglycerides-increasing alleles of GCKR variants rs1260326 and rs1260333 lowered insulin and HOMA-IR, and reduced the risk of insulin resistance in Chinese descent children." (PMID 23383164, 2013). "CAH patients are characterized by insulin resistance, lower insulin sensitivity and hyperinsulinemia." (PMID 23379763, 2013). "Even so, insulin resistance has been closely related to reduced metabolic responsiveness to normal insulin circulation." (PMID 24324517, 2013). "For this reason, we used the T2DM rat model to investigate the mechanisms of DACD as well as CNS insulin resistance and insulin signaling transduction." (PMID 23829668, 2013). "For example, in Sepp1-injected mice, endogenous glucose production increased, peripheral glucose disposal decreased, glucose intolerance and insulin resistance were induced and blood insulin levels were significantly elevated." (PMID 23760059, 2013). "A higher level of insulin resistance within the liver is associated with IFH; whereas, impairment of early phase insulin secretion and total insulin secretion in response to glucose were worse in subjects with IPH." (PMID 23990951, 2013). "The development of insulin resistance and diabetes, under the condition of chronic excessive GH, is at least partially attributable to the interference of GH with insulin signaling." (PMID 23840818, 2013). "It is considered that the improved insulin resistance conferred by beta-glucan contributed to the suppressive effect on high-fat and high-fructose diet which induced impaired glucose tolerance and insulin sensitivity." (PMID 24371433, 2013). "By and large, available evidence suggests that insulin has mood-enhancing effects or point to a positive correlation between insulin resistance and depression." (PMID 24109426, 2013). "Age, BMI, cholesterol, glucose, insulin, glycohemoglobin, and homeostasis model assessment of insulin resistance values significantly increased in NASH patients." (PMID 24324749, 2013). "The results were described as hepatic insulin resistance, that is, more insulin was needed to maintain the level of blood glucose in the presence of fructose and, conversely, high insulin did not repress production of glucose." (PMID 23815799, 2013). "Exposure to low concentrations of carrageenan (10 μg/mL in the water supply) has produced glucose intolerance, insulin resistance, and impaired insulin signaling in C57BL/6 mice." (PMID 23766559, 2013). "We created a model of insulin resistance by exposing HepG2 cells to high concentrations of glucose and examined the effect of NaB under insulin-resistance conditions." (PMID 23696823, 2013). "Several evidences show that NAFLD development is associated with the amount of visceral fat, AST, ALT, total cholesterol, triglycerides, serum insulin and insulin resistance, which is assessed by the HOMA-IR." (PMID 23816341, 2013). "High infant weight gain was positively related with high insulin levels as well as high HOMA-IR later on (homeostasis model assessment of insulin resistance)." (PMID 24265718, 2013). "Since NAFLD and insulin resistance are closely associated, we linked and studied the action of GSP along with MET, an insulin sensitizer, on lipid abnormalities." (PMID 24307947, 2013). "For example, activation of proinflammatory pathways in adipose tissue is known to interfere with insulin signaling and induce hepatic insulin resistance." (PMID 23762871, 2013).
Insulin resistance (continued). "HOMA-IR, an indirect estimate of insulin resistance, is usually used to represent the inhibition of hepatic glucose output by insulin, which is maintained by a balance between the liver and β-cells." (PMID 23688034, 2013). "It is well known from a number of clinical studies that increased fat mass decisively contributes to the development of insulin resistance, accompanied with increased plasma insulin and triglyceride levels, as observed here experimentally." (PMID 24265718, 2013). "Skeletal muscle is a major target tissue for GC-induced insulin resistance and is responsible for about 80% of insulin-stimulated total glucose disposal." (PMID 24312573, 2013). "The anti-inflammatory action of Foxp3+ T cells (Tregs) has been proposed to alter insulin sensitivity, as obesity is accompanied by both a reduction in the proportion of this T cell population and the development of insulin resistance." (PMID 23562076, 2013). "Insulin resistance in insulin sensitive tissues is an early pathophysiologic feature in T2D, and interventions to improve insulin sensitivity are of paramount important for the cure of T2D." (PMID 24349514, 2013). "Leucine activates mTOR pathways that can inhibit early steps in insulin signaling pathways, leading to insulin resistance." (PMID 24023709, 2013). "The highest correlations were observed between PAi-1 or tPA and the measures of insulin resistance: fasting insulinemia, insulin AUC and HOMA-IR, Spearman correlation coefficients ranged between 0.67 and 0.71 (p < 0.001 for all correlations)." (PMID 23870459, 2013). "Heterozygous deficiency of dihydroceramide desaturase (DES1) had improved insulin sensitivity and dexamethasone-induced insulin resistance was prevented." (PMID 23761785, 2013). "Type 2 diabetes is preceded by the inability of β-cells to secrete sufficient insulin to overcome insulin resistance or reduced insulin sensitivity, combined with reduced insulin secretion." (PMID 24137248, 2013). "The Spleen Qi deficiency with Damp cohort had statistically significant higher fasting glucose, higher insulin, higher insulin resistance, higher HbA1c and lower HDL than those with Qi and Yin deficiency." (PMID 23762155, 2013). "T2DM is described as a “silent disease” and is characterized by the combination of inadequate insulin secretion due to islet β-cell deterioration and insulin resistance." (PMID 24282409, 2013). "At adulthood, higher plasma insulin and glycemia in macrosomic rats, only the female macrosomic rats, showed abnormal glucose response due to peripheral insulin resistance." (PMID 23878822, 2013). "Endothelial dysfunction is intricately related to insulin resistance through the stimulatory effects of insulin on glucose disposal and NO production in the endothelium." (PMID 23484099, 2013). "Further studies such as glucose tolerance test and insulin tolerance test are needed to examine possible effects of BOF on pancreatic insulin secretion and insulin resistance in KKAy mice." (PMID 24130717, 2013). "A significant increase in fasting glucose and insulin levels as well as development of insulin resistance was observed in ANXA1 KO mice on HFD compared to WT mice." (PMID 24312665, 2013). "In obese children, serum vaspin levels are positively correlated with TG, fasting insulin, and homeostatic model assessment of insulin resistance (HOMA-IR)." (PMID 24145612, 2013). "Several studies have shown decreased insulin resistance and increased insulin sensitivity in 12Ala carriers." (PMID 23559865, 2013). "Results demonstrate the onset of adipose insulin resistance in late-fasted elephant seal pups and suggest that the phenomenon manifests through the impairment of adipose insulin signaling due to the intracellular accumulation of DAG." (PMID 23997935, 2013). "MiR-125a is suggested to contribute to insulin resistance and play a critical role in insulin signaling through affecting genes involved in the MAPK signaling pathway implicated in T2D." (PMID 23878802, 2013).
Insulin resistance (continued). "Lots of studies reported that a strong positive correlation exists between the concentration of leptin and insulin sensitivity and obesity, but the anti-insulin resistance effect of leptin, independently of its activity on weight control, was also reported." (PMID 23762871, 2013). "Peripheral administration of IL-6 interrupts insulin signaling due to enhance expression of SOCS3 in hepatocytes suggesting that obesity-induced IL-6 expression mediates insulin resistance." (PMID 23781214, 2013). "Growing Drosophila on a high sucrose medium produces a model of insulin resistance which can be directly demonstrated on insulin signaling in larvae." (PMID 23690925, 2013). "Development of insulin resistance basically occurs in insulin-dependent tissues thus spare glucose for metabolism in non-insulin dependent organs." (PMID 23853618, 2013). "The insulin tolerance test indicates overall reduction in insulin resistance in CNX-011-67 treated rats." (PMID 23692921, 2013). "Examination of the biological mechanisms through which sTWEAK improves insulin sensitivity has demonstrated that, in visceral adipocytes, treatment with sTWEAK ameliorates TNFα-induced insulin resistance on glucose uptake." (PMID 24416031, 2013). "The insulin resistance of TLR2 KO mice was accompanied by a down-modulation of insulin-induced insulin signaling in the liver, muscle, and adipose tissue, associated with an increase in endoplasmic reticulum stress." (PMID 23482058, 2013). "Although insulin signaling is well studied, the molecular mechanisms how insulin resistance develops are still unclear." (PMID 23781214, 2013). "The pathogenesis of type 2 DM is complex, involving progressive development of insulin resistance in peripheral tissues accompanied by defective insulin secretion from pancreatic beta cells leading to overt hyperglycemia." (PMID 23360495, 2013). "In the present study, LET prevented the increase of circulating triglycerides and insulin resistance, reinforcing the role of physical training on lipid control and storage, as well as on the insulin sensitivity." (PMID 23777435, 2013). "Signs of insulin resistance were also evident in cases, such as elevated waist circumference, high insulin levels and HOMA index." (PMID 23874450, 2013). "The AI extract effectively reversed the HFD-induced elevations in plasma glucose and insulin levels and the homeostasis model assessment of insulin resistance index." (PMID 23401719, 2013). "Higher blood glucose and insulin levels in HFD group indicate the insulin resistance in these animals." (PMID 23533447, 2013). "In fully compensated insulin resistance, there is a sufficient upregulation of insulin secretion whereas in glucose intolerance and type 2 diabetes this upregulation is inadequate." (PMID 23781322, 2013). "High circulating FFA levels can also lead to pro-inflammatory processes that impair insulin signaling in liver, adipose, and skeletal muscle leading to insulin resistance." (PMID 26029481, 2013). "One common property of human obesity and NIDDM is insulin resistance, in which a given amount of insulin produces less than normal physiological responses." (PMID 27335827, 2013). "The authors found that PTEN transgenic mice, both young and old, had lower fasting levels of glucose and insulin serum levels, and a significantly lower value of the insulin resistance index HOMA-IR compared with the wild type control mice." (PMID 28548055, 2013). "Serum FFAs, which are elevated in most obese subjects, induce metabolic insulin resistance and inhibit insulin signaling through different mechanisms." (PMID 23360495, 2013). "When on an obesity-inducing diet, Sepp1−/− mice were protected against glucose intolerance and insulin resistance and serum levels of free fatty acids and insulin were significantly reduced." (PMID 23760059, 2013). "Some evaluate insulin resistance state indirectly by measuring the index of insulin sensitivity (Si)." (PMID 23424687, 2013).